BISPR (BST2 interferon stimulated positive regulator)
Synonyms: lncBST2
Gene: Long non-coding RNA gene on chromosome 19 (17,405,686 to 17,419,324, forward strand). Ensembl gene ENSG00000282851.
Diseases named in the same sentence as BISPR in open-access papers:
BISPR is named in the same sentence as 9 diseases in open-access papers, as found by Europe PMC text mining. Sharing a sentence is not in itself a finding about the gene and the disease. The quoted sentences say what the papers report.
Viral infections (2 papers, 2014 to 2023). "IFNs are notoriously important immune regulators of viral infections and appear to regulate BISPR expression." (PMID 37922302, 2023).
arboviral diseases (1 paper, 2023). "Expression of BISPR, BST2, and OASL in other arboviral diseases." (PMID 37922302, 2023).
COVID-19 (1 paper, 2025). A disease caused by infection with severe acute respiratory syndrome coronavirus 2. "The observed upregulation of GAS5, NORAD, BISPR, and NEAT1 in dRNA-seq of infected Calu-3 cells (1.03- and 1.11-fold) is consistent with upregulation of these lncRNAs in COVID-19 patients (1.05- and 1.17-fold) in the two datasets (GSE171110 and GSE157103)." (PMID 41267684, 2025). "The upregulation observed of GAS5, NORAD, BISPR, and NEAT1 in dRNA-seq of infected Calu-3 cells (between 1.03- and 1.11-fold) is consistent with upregulation of these lncRNAs in COVID-19 patients (1.05- and 1.17-fold) in the two datasets (GSE171110 and GSE157103)." (PMID 41267684, 2025).
Dengue (1 paper, 2023). "Expression of BISPR, OASL, and BST2 were upregulated during acute Dengue and Zika infection, similarly to what we observed in acute Chikungunya infection." (PMID 37922302, 2023).
hepatitis C virus infection (1 paper, 2020). A viral infection caused by the hepatitis C virus. "In HuH7 cells derived from human hepatocarcinoma, both lncISG15 and lncBST2/BISPR were identified upon IFNα2 treatment and were also induced by hepatitis C virus infection." (PMID 32528521, 2020).
hepatoma (1 paper, 2017). "This reveals a pattern of temporal alterations of BISPR and BST2 (Tetherin) in HEV infected hepatoma cells in line with HEV replication cycle described earlier." (PMID 29091957, 2017).
infection (3 papers, 2014 to 2025). The state of being infected such as from the introduction of a foreign agent such as serum, vaccine, antigenic substance or organism. "The observed loss of the m6A modification in BISPR post-infection may indicate a decrease in m6A-mediated decay, therefore enhancing transcript stability and enabling its upregulation and cis-mediated regulation of BST2." (PMID 41267684, 2025). "To determine whether lncISG15 and lncBST2/BISPR respond to infection only in HuH7 cells or whether this effect is specific for influenza viruses, we infected alveolar epithelial A549 cells with VSV-GFP wild-type virus or with a M51R matrix mutant that fails to control IFN." (PMID 25620967, 2014). "The expressions of lncRNAs UCA1, GAS5, NORAD, BISPR, and NEAT1 were quantified using Illumina cDNA (RNA-seq) sequencing data and compared to dRNA-seq using fold change expression in infection (normalized reads in infected/normalized reads in uninfected)." (PMID 41267684, 2025). "CHROMR expression was similarly upregulated by IAV and SARS-CoV-2, infection, while other lncRNAs that were tested were preferably enhanced by either IAV (BISPR, NRIR, CCR5AS) or SARS-CoV-2 (LUCAT1) infection." (PMID 40559622, 2025). "In fact, we show that lncBST2/BISPR and BST2 are induced after infection with HCV or influenza and VSV mutant viruses that activate the IFN response." (PMID 25620967, 2014). "BISPR, which showed upregulation at the transcriptional level, has a m6A methylated site (P = 60%) in uninfected cells, but no methylation sites were detected post-infection." (PMID 41267684, 2025). "The results showed that at later times post-infection with the influenza virus lacking NS1, there was increased expression of lncISG15, lncBST2/BISPR, and their neighboring coding transcripts." (PMID 25620967, 2014).
BISPR also shares sentences with these, for which no sentence is quoted: chronic myeloid leukemia (1 paper); thyroid papillary carcinoma (1).